ATF3 (activating transcription factor 3)
Diseases named in the same sentence as ATF3 in open-access papers (continued):
Sharing a sentence is not in itself a finding about the gene and the disease.
viral infection (18 papers, 2017 to 2025). "Finally, Atf3 promotes cellular growth, invasion, and collagen synthesis, while inhibiting apoptosis, playing a crucial role in the lung, as demonstrated by its association with protection against acute pulmonary injury and viral infection." (PMID 34872491, 2021). "For virus infections, ATF3 expression can produce anti-viral outcomes by regulating the transcription of host antiviral genes." (PMID 39212382, 2024). "ATF3 upregulation during viral infections promotes a stronger immune response and increased resistance in various mammalian species including mice and humans." (PMID 39211041, 2024). "Recent research has revealed the dual role of ATF3 in viral infections, where it can inhibit viral replication and can also be exploited by viruses to enhance their replication." (PMID 38255898, 2024). "Mammalian ATF3 is activated by cellular stress response pathways and plays a role in the host’s immune response to viral infections." (PMID 39211041, 2024). "In order to minimize artificial effects induced by overexpressed ATF3, the HDF line with the lowest expression of ATF3 after virus infection (strain 0808) was used for the following studies." (PMID 32373541, 2020). "Similarly, stress response and apoptosis-related genes FOS, JUN, and activating transcription factor 3 (ATF3) show increased expression in severe cases, highlighting the role of NK cells in modulating cell death pathways in response to viral infection." (PMID 39928675, 2025). "During viral infection, the activation of ATF3 produces paradoxical outcomes (35, –, 37)." (PMID 39212382, 2024). "Furthermore, it has been suggested that ATF3 is involved in glucose metabolism, an important pathway during viral infections." (PMID 39637135, 2024). "ATF3 regulates viral infection by stimulating and inhibiting immune responses." (PMID 38255898, 2024). "Furthermore, the results indicate for the first time that virus infection induces ATF3, which is able to interact directly with the HLA-G promoter, finally inducing the HLA-G production associated to virus infection." (PMID 30523283, 2018). "This suggested that JEV replication was necessary and various signalling pathways might have an additive effect towards the induction of ATF3 during the viral infection." (PMID 28821775, 2017). "Interestingly, using a neuronal cell line that is deficient in IFN I synthesis ATF3 upregulation is observed in response to viral infection; implying the IFN signaling is not strictly required for inducing ATF3 expression." (PMID 37033378, 2023). "However, when the ISR pathway is inhibited, ATF3 protein expression may be upregulated, through either enhanced cap-dependent translation or mechanisms stabilizing the protein, which could control the cellular stress induced during viral infection." (PMID 39212382, 2024). "In another set of animals, following 2 d virus infection, rats were subjected to 35 min of MCA occlusion, and ATF3 protein expression determined at 24 h of reperfusion in the ischemic cortices." (PMID 36768628, 2023). "Knocking down ATF3 neither affected the basal VSVΔ51 infectivity levels nor altered the capacity of 4-OI to promote virus infection." (PMID 38750019, 2024). "In addition to HMGB1 and ATF3, other target genes at the HBV/HCV shared GWS loci are involved in both autophagy and immune signaling pathway to virus infection." (PMID 34458256, 2021). "We further demonstrated that in the absence of ATF3, the levels of ZIKV protein, RNA, and virions increased, indicating that ATF3 functioned to restrict viral infection." (PMID 39212382, 2024).
ovarian carcinoma (16 papers, 2010 to 2025). A malignant neoplasm originating from the surface ovarian epithelium. "After stably expressing a luciferase vector in ovarian cancer cells that encoded the ATF3 3 ́-untranslated region sequence, we observed a significant reduction in luciferase among SKOV-3 cells transfected with miR-30c-2-3p, but not those also transfected with the neutralizing anti-miR-30c-2-3p." (PMID 26418018, 2015). "Research indicated that cells from recurrent solid tumors demonstrated increased expression of ATF3, implying its role in promoting ovarian cancer aggressiveness, treatment resistance, and recurrence." (PMID 40612060, 2025). "In this study, we investigated how C. majus engages in ovarian cancer cell apoptosis by activating the ATF3-Tip60 pathway." (PMID 35283423, 2022). "The assessment of primary ovarian tumor gene expression revealed that the expression of ATF3 mRNA is directly correlated with symptoms of depression in patients suffering from ovarian carcinoma." (PMID 35814375, 2022). "Further research will be needed to identify transcriptional targets of ATF3 following chemotherapy exposure in ovarian cancer." (PMID 36131935, 2022). "Remarkably, there have been very few studies that have specifically investigated the mechanistic role of ATF3 in ovarian cancer." (PMID 36131935, 2022). "Our results demonstrate the process by which C. majus-mediated ATF3 induces Tip60 and promotes Foxo3a nuclear translocation, leading to apoptosis in human ovarian cancer cells via the caspase-3-dependent pathway." (PMID 35283423, 2022). "We utilized The Cancer Genome Atlas (TCGA) Firehose Legacy ovarian cancer cohort to determine which genes ATF3 is correlated with in a large HGSOC cohort." (PMID 36131935, 2022). "ATF3 is a potential target gene of estrogen in sexual differentiation, and it is involved in progesterone-related ovarian cancer and luteal regression." (PMID 28577574, 2017). "To commence our investigation, we added lysophosphatidic acid (5 μM) to SKOV-3 ovarian cancer cells and measured an increase in ATF3 protein levels and ATF3 mRNA transcripts, over 8 h." (PMID 26418018, 2015). "We show that the overexpression of ATF3 significantly reduces the number of ovarian cancer cells, which suggests an influence on proliferation–a hallmark of cancer." (PMID 26418018, 2015). "Taken together, this data suggests that in ovarian cancer cells, lysophosphatidic acid stimulation induces the expression of ATF3." (PMID 26418018, 2015). "This reinforces the role of ATF3 and intimates an important contextual function among patients with ovarian cancer, especially since stress promotes the progression of ovarian cancer." (PMID 26418018, 2015). "In contrast, among some ovarian cancer cells, ATF3 functions as an apoptosis inducer, yet in other ovarian cancer cells it belongs to a profile of worsened outcomes." (PMID 26418018, 2015). "Moreover, in some types of ovarian cancer, ATF3 promotes the apoptosis mechanism, but in others, it is associated with poor prognosis outcomes." (PMID 35814375, 2022). "So these findings reveal the functional role of ATF3 in primary ovarian carcinoma." (PMID 35814375, 2022). "However, the purpose of this study was to confirm the interaction between ATF3 and miR-30c-2-3p, thereby further establishing the role of miR-30c-2-3p after induction by lysophosphatidic acid in ovarian cancer cells." (PMID 26418018, 2015). "This study demonstrates that upon infiltrating the ovarian cancer TME, NK cells activate an integrated stress response (ISR) centered on ATF3." (PMID 40959272, 2025). "Interestingly, while both EGR1 and ATF3 are well studied as stress-responsive transcription factors, ATF3 emerged as a gene of interest since it is a master transcription factor that regulates immunity and inflammation, but little is known about its role in ovarian cancer." (PMID 36131935, 2022).
ovarian carcinoma (continued). "In contrast to ATF3, the role of Amphiregulin (AREG), which is a low affinity ligand for epidermal growth factor receptor (EGFR), has been more established in ovarian cancer." (PMID 36131935, 2022). "In contrast, low expression of ATF3 has been reported in ovarian cancer cells compared to non-cancerous ovarian epithelial cells." (PMID 38658567, 2024). "In contrast to our results for ovarian cancer cells, Western blot analysis did not shown upregulation of BiP or ATF3 in nelfinavir-treated leukemia cells, and cells exhibited no signs of autophagy as shown by a lack of LC3B upregulation." (PMID 20105315, 2010).
pancreatic cancer (16 papers, 2010 to 2025). "In many cancers, including pancreatic cancer, cells of the tumour microenvironment affect progression of cancer pathology and scRNA-seq identified ATF3 in subsets of fibroblasts and immune cells for both murine and human models of PDAC." (PMID 41198649, 2025). "Overall, this assessment underscores the complexity of ATF3 within pancreatic cancer and highlights the importance of context in determining ATF3’s role in carcinogenesis." (PMID 41198649, 2025). "We have previously reported that decreased ATF3 expression is correlated with poor differentiation and shorter overall survival in PAAD patients, indicating that ATF3 is essential to the progression of pancreatic cancer." (PMID 36615000, 2022). "RNA sequencing analysis also showed that gossypol increased the mRNA levels of CCAAT/enhancer-binding protein homologous protein (CHOP) and activating transcription factor 3 (ATF3) in pancreatic cancer cell lines." (PMID 35283426, 2022). "For example, lncRNA-ZNFTR inhibits pancreatic cancer cells by regulating the ATF3/ZNF24/VEGFA pathway." (PMID 35647035, 2022). "For example, in pancreatic cancer cells, Celastrol plays a cytotoxic role by regulating various gene expressions, mainly through ATF3/DDIT3 overexpression and RRM2/MCM4 downregulation." (PMID 36506508, 2022). "In our study, we found that gossypol treatment markedly upregulated the expression of PPP1R15A, Tribbles-related protein 3 (TRIB3), and ATF3 in pancreatic cancer cells." (PMID 35283426, 2022). "The results show that therapeutic Hsp90 inhibition substantially up-regulates the expression of ATF3 in various cancer cells, including colon, gastric and pancreatic cancer." (PMID 21129190, 2010). "NAD limitation could increase ATF3 expression by reducing sirtuin activity and increasing histone acetylation, a process that is known to regulate ATF3 expression in pancreatic cancer cells." (PMID 36428689, 2022). "In a word, this study demonstrates that KLF6 inhibits the progression of pancreatic cancer through upregulating ATF3 and may serve as a potential therapeutic target." (PMID 36615000, 2022). "Meanwhile, these results also indicate the potential function of ATF3 on pancreatic cancer cell." (PMID 36615000, 2022). "To determine whether KLF6 is involved in pancreatic cancer progression through ATF3, we performed rescue experiments." (PMID 36615000, 2022). "Furthermore, KLF6 can inhibit the progression of pancreatic cancer by upregulating ATF3." (PMID 36615000, 2022). "Meanwhile, in pancreatic cancer, HIF-1α-induced lncRNA-MTA2TR (MTA2 transcriptional regulator RNA) transcriptionally up-regulates the expression of oncogenic MTA2 (metastasis associated protein 2) by recruiting ATF3 (activating transcription factor 3) to the promoter area of MTA2." (PMID 32370770, 2020). "Under hypoxic conditions, downregulation of ZNFTR expression decreases ZNF24 expression via ATF3, resulting in the upregulation of VEGFA, which promotes pancreatic cancer progression." (PMID 39790557, 2025). "ZNF24 can interact with activating transcription factor 3 (ATF3) and acts as a tumor suppressor protein in pancreatic cancer." (PMID 37986084, 2023). "It has also been shown the anti-pancreatic cancer activity of celastrol by up-regulating DDIT3 and ATF3 and down-regulating RRM2 and MCM4, however, the role of celastrol in anti-pancreatic cancer remains largely elusive." (PMID 38110764, 2023). "ZNFTR interacts with ATF3 to sequester ATF3 away from the ZNF24 promoter, increase ZNF24 expression, and downregulate VEGFA transcription, thereby reducing the proliferative, metastatic, and proangiogenic abilities of pancreatic cancer cells." (PMID 39790557, 2025). "Therefore, although gossypol promotes apoptosis in various cancer cells, ER stress signaling is induced specifically in pancreatic cancer cells via regulation of PPP1R15A, TRIB3, and ATF3 gene expression." (PMID 35283426, 2022).
pancreatic cancer (continued). "However, the specific and detailed molecular mechanisms of how ATF3 is regulated by KLF6 and other potential mechanisms in pancreatic cancer need more research." (PMID 36615000, 2022).
liver cancer (15 papers, 2010 to 2026). An epithelial or non-epithelial malignant neoplasm that arises from the liver. "Then, we performed ROC analysis to evaluate the diagnostic potency of ATF3 which demonstrated that ATF3 was a moderate predictor in liver cancer (AUC = 0.769, CI = 0.694–0.845)." (PMID 37580343, 2023). "To further elucidate the relationship between VPS72 and ATF3 expression, as well as their connection to mTORC1 activity in liver cancer, we conducted data mining of liver cancer expression datasets." (PMID 40305746, 2025). "The DSS analysis results displayed that liver cancer patients with high expression of ATF3, ACSL1, and LPIN1 exhibited significantly longer DSS." (PMID 37580343, 2023). "In aggregate, we reported a sophoridine derivative 6j which displayed a strong anti-liver cancer effect via ATF3 mediated ferroptosis." (PMID 37580343, 2023). "Prognostic value of ATF3 mRNA expression in patients with liver cancer was determined using Kaplan–Meier plot." (PMID 33407456, 2021). "Targeted gene analysis from public online database revealed multi-level evidence of the importance of ATF3 in liver cancer development and supported its role as a biomarker in HCC." (PMID 33407456, 2021). "Analysis of the TCGA LIHC database revealed a negative correlation between VPS72 and ATF3 expression, indicating that VPS72 amplification may downregulate ATF3 in liver cancer." (PMID 40305746, 2025). "Notably, tumors with VPS72 copy number gain (>median expression) and ATF3 loss (<median expression) exhibited heightened mTORC1 activation, suggesting that mTORC1 signaling is a downstream target of VPS72 amplification in liver cancer." (PMID 40305746, 2025). "In the present study, we disclosed that a sophoridine derivative 6j could upregulated the expression of ATF3 via ER stress in liver cancer cell." (PMID 37580343, 2023). "Next, we evaluated the expression of ATF3 in liver cancer cells upon 6j treatment." (PMID 37580343, 2023). "Our results suggest that upregulation of ATF3 by 6j could be a potential effective approach to treat liver cancer." (PMID 37580343, 2023). "In addition, we elaborate on the roles of ATF3 as a regulator of prostate, breast, colon, lung, and liver cancers." (PMID 32922364, 2020). "Further understanding of how ATF3 regulates signaling pathways involved in glucose metabolism, adipocyte metabolism, immuno-responsiveness, and oncogenesis in various cancers, including prostate, breast, colon, lung, and liver cancers, is then provided." (PMID 32922364, 2020). "ATF3 plays an important role in modulating immune homeostasis, glucose and adipose tissue regulation, and cell proliferation and metastasis in breast, prostate, colon, lung, and liver cancers." (PMID 32922364, 2020). "Previous studies revealed that ATF3 could impede the tumorigenesis and progression of liver cancer." (PMID 37580343, 2023). "Therefore, we used TIMER to study whether the expression of ATF3 is related to the level of infiltrating lymphocytes in liver cancer." (PMID 33407456, 2021). "Therefore, ATF3 high expression levels observed in the liver of JDP2-transgenic mice may a play a positive role at the tumor promotion stage of liver cancer." (PMID 20214788, 2010). "On the other hand, previous literatures revealed that CDCA8 affects liver cancer progression through E2F1 and ATF3." (PMID 36639822, 2023). "By analyzing RNA-seq data from TCGA and GTEx, we discovered that ATF3, ACSL1, LPIN1, and DDR2 were significantly downregulated while DDIT3 was upregulated in liver tumor compared with normal tissues, implying that these five genes might be associated with liver cancer." (PMID 37580343, 2023).
acute kidney injury (14 papers, 2016 to 2026). Sudden and sustained deterioration of the kidney function characterized by decreased glomerular filtration rate, increased serum creatinine or oliguria. "In another study, quercetin was found to increase the levels of SLC7A11 and GPX4 expression and subsequently enhance cell viability, by inhibiting ATF3, thereby reducing the risk of acute kidney injury (AKI)." (PMID 39171207, 2024). "ATF3 has been reported to protect against acute kidney injury by modulating inflammatory responses and apoptosis." (PMID 41369384, 2025). "Quercetin, which decreases the expression of ATF3, could alleviate acute kidney injury via inhibition of ferroptosis." (PMID 37056514, 2023). "It was initially identified in isolated renal tubular tissue from acute kidney injury (AKI) model and involved in the inflammatory progression in AKI's early stage via circZNF644/miR-494/ATF3 axis." (PMID 38966668, 2024). "Using animal models of acute kidney injury (AKI), activating transcription factor 3 (ATF3) and Fetuin A were identified as candidate protein biomarkers in uEVs, and they were also confirmed in human adult AKI." (PMID 38093081, 2024). "For example, miR-494 was increased in the serum and urine during acute kidney injury in patients, however, it can promote ischemic AKI through targeting ATF3." (PMID 35166173, 2022). "ATF3 was demonstrated interacted directly with histone deacetylase 1 (HDAC1) and recruited HDAC1 into the ATF/NF-κB sites in the IL-6 and IL-12b gene promoters to protect against acute kidney injury." (PMID 28912732, 2017).
bladder cancer (14 papers, 2013 to 2025). "KDM6A-deficient bladder cancer cell lines show a loss of interaction with FOXA1, normally involved in urothelial differentiation, and a redistribution of transcription factor ATF3, further repressing FOXA1-target genes and activating cell cycle progression." (PMID 38540132, 2024). "Conversely, other studies have demonstrated that ATF3 functions as a tumor suppressor in other cancers that include esophageal, colon, and bladder cancers." (PMID 34631548, 2021). "In bladder cancer, ATF3 suppresses metastasis of bladder cancer by regulating gelsolin-mediated remodeling of the actin cytoskeleton." (PMID 30376856, 2018). "In the present study, T24 bladder carcinoma cells showed the biphasic increases of UPR genes ATF3 and ATF4." (PMID 23560094, 2013). "Overexpression of ATF3 in highly metastatic bladder cancer cells decreases migration in vitro and in vivo." (PMID 24260584, 2013). "ATF3 has recently been shown to suppress metastasis of bladder cancer through regulating Gelson-mediated remodeling of the actin cytoskeleton." (PMID 24260584, 2013). "Furthermore, METTL1 can also modify miR-760 in an m7G-dependent manner to suppress ATF3 mRNA expression, thereby contributing to the progression of bladder cancer." (PMID 40809690, 2025). "In BCa, ATF3 has been found to regulate gelsolin-mediated remodeling of actin cytoskeleton to suppress tumor metastasis amd can be utilized as a potential marker of the response to histone deacetylase inhibitor mediated therapy in bladder cancer." (PMID 36396627, 2022). "Interestingly, AREG, ATF3, ZFP36, and DUSP1 were all associated with inflammation and cancer, specifically enrichment of adipocytokine signaling, bladder cancer, epithelial cell signaling in Helicobacter pylori infection, and JAK/STAT signaling pathways in patients with high AREG expression." (PMID 35372438, 2022). "In the context of bladder cancer, METTL1 is involved in m7G modification of miR-760, leading to the suppression of ATF3 mRNA expression." (PMID 40809690, 2025).